FADD (Fas associated via death domain)
Diseases named in the same sentence as FADD in open-access papers (continued):
Sharing a sentence is not in itself a finding about the gene and the disease.
periodontitis (2 papers, 2020 to 2022). An acute or chronic inflammatory process that affects the tissues that surround and support the teeth. "Hypermethylation was found in TLR regulators genes: MAP3K7, MYD88, IL6R, RIPK2, FADD, IRAK1BP1, and PPARA in early stages of periodontitis, while advanced stages presented hypomethylation of these genes." (PMID 36233348, 2022).
primary immunodeficiencies (2 papers, 2016 to 2019). "Germline mutations in human caspase-8 or its key adapter FADD cause a primary immunodeficiency associated with severe recurrent bacterial infections, encephalopathy and hepatopathy." (PMID 27737018, 2016).
sarcoma (2 papers, 2016 to 2020). A usually aggressive malignant neoplasm of the soft tissue or bone. "To see if FADD−/− DCs vaccine works in another syngeneic tumor model and by using a more physiological antigen for vaccines, we employed MCA303 sarcoma." (PMID 32663380, 2020).
Anxiety (1 paper, 2023). Intense feelings of nervousness, tension, or panic often arise in response to interpersonal stresses. "Arguably, the aberrant stimulation of MAPKs, FADD, and Akt/mTOR signaling pathways may rather contribute to stress-mediated changes in gene expression profiles and the subsequent neuroadaptations underlying the anxiety-like behavioral responses." (PMID 36768626, 2023).
brain tumors (1 paper, 2010). "The present study aimed to explore the clinical feasibility of this vector in the treatment of human brain tumors by placing the FasL or FADD genes under the regulation of a glial cell-specific promoter." (PMID 20942909, 2010).
Cachexia (1 paper, 2019). Severe weight loss, wasting of muscle, loss of appetite, and general debility related to a chronic disease. "Similarly, these results suggest that the increase in ANGPTL-4 and decrease in FADD in the tumor may be associated to advance of cachexia in cancer patients." (PMID 31741709, 2019). "Previously, we found an increase in FADD levels in peritumoral adipose tissue in cancer cachexia patients in comparison to cancer patients with a stable weight; however, we detected a decrease in this factor in the CC group as compared to the WSC group." (PMID 31741709, 2019).
chronic granulomatous disease (1 paper, 2025). Chronic granulomatous disease (CGD) is a rare primary immunodeficiency, mainly affecting phagocytes, which is characterized by an increased susceptibility to severe and recurrent bacterial and fungal infections, along with the development of granulomas. "Sixteen cases (45.7%) were confirmed to have PID, including SCID (7 cases, 20.0%), chronic granulomatous disease (6 cases, 17.1%), Mendelian susceptibility to mycobacterial disease (2 cases, 5.7%), and fas associated via death domain (FADD) gene mutation (1 case, 2.6%)." (PMID 40470261, 2025). "Six cases (37.5%) had chronic granulomatous disease (CGD) due to CYBB gene mutations, 2 cases (12.5%) had Mendelian susceptibility to mycobacterial disease (MSMD) due to IL12RB1 mutations, and 1 case (6.25%) had a FADD gene mutation." (PMID 40470261, 2025).
clear cell renal cell carcinoma (1 paper, 2022). "FADD-mediated apoptosis may suppress carcinogenesis in clear cell renal cell carcinoma." (PMID 36348274, 2022).
cognitive decline (1 paper, 2017). "Because the onset of cognitive decline was somewhat variable, we performed random-effects models to evaluate the potential association between longitudinally ascertained cognitive decline rates and postmortem cortical immunodensities of FADD, adjusting for demographics and neuropathologies." (PMID 28320441, 2017). "However, none of these studies explored the potential link between brain FADD (or other apoptotic markers) variations and cognitive decline or AD-related pathology." (PMID 28320441, 2017).
cognitive disease (1 paper, 2022). "Interestingly, when we considered proteins which were significantly different in their SD between the healthy old and the old with cognitive disease and between the healthy young and healthy old, there were just 4 such proteins: Smad5, uPAR, FADD, and TGFBR1." (PMID 35999337, 2022).
cryptococcal infection (1 paper, 2017). "Having demonstrated that RIPK3 and RIPK3/FADD deletions altered inflammatory infiltrate compositions, we further examined the roles of RIPK3 and FADD in pulmonary and systemic cytokine levels during cryptococcal infection." (PMID 28919893, 2017). "Using a mouse model of cryptococcal infection, the roles of FADD and RIPK3 in anti-cryptococcal defense were investigated." (PMID 28919893, 2017). "Our first group of studies elucidated the involvement of both RIPK3 and FADD during cryptococcal infection." (PMID 28919893, 2017). "Thus, both RIPK3 and FADD significantly contributed fungal containment during pulmonary cryptococcal infection." (PMID 28919893, 2017). "Here, we explored the roles of FADD and RIPK3 in a mouse model of cryptococcal infection and identified previously unknown, critical contributions of these molecules in pulmonary immune responses to cryptococcal infection." (PMID 28919893, 2017).
esophageal carcinoma (1 paper, 2022). A primary or metastatic malignant neoplasm involving the esophagus. "In contrast, the high expression of TLR3 in KIRC, ACC, MESO, esophageal carcinoma (ESCA), and uterine carcinosarcoma (UCS); FASLG in HNSC, BLCA, and STAD; RIPK3 in COAD; RIPK1 in MESO and KIRP; FAS in ACC; and FADD in THCA was associated with good survival." (PMID 35748782, 2022).
fungal infection (1 paper, 2017). "Collectively, these data indicated that C. neoformans infection affected apoptotic rates of certain leukocyte subsets, but only the joint FADD/RIPK3 deletion led to detectable alterations in the APF in these leukocyte subsets during fungal infection." (PMID 28919893, 2017). "Collectively, our study shows that RIPK3 and FADD factors are crucial elements of regulatory network that allows protecting the host from pathological effects of inflammation while supporting clearance of the invasive fungal infection." (PMID 28919893, 2017). "Together, these findings document that responses “designed” to be protective in fungal infections can become highly detrimental to the host, and our data demonstrate such detrimental outcomes following RIPK3 and FADD deletion." (PMID 28919893, 2017). "Collectively, these findings establish a novel link between these PCD components and immune response to cryptococcal challenge, demonstrating the crucial importance of FADD and RIPK3 in maintaining immune homeostasis during invasive fungal infection." (PMID 28919893, 2017). "While PCD pathway components were shown to be important regulators of the immune responses, the role of FADD and RIPK3 in host defenses against fungal infection remained unknown up to this point." (PMID 28919893, 2017). "This novel link between the protective effect of FADD and RIPK3 in antifungal defense and sustenance of immune homeostasis may be important for the development of novel immunomodulatory therapies against invasive fungal infections." (PMID 28919893, 2017). "Thus, while future studies are needed to provide definitive answers, our data favor the hypothesis that RIPK3 and FADD can induce immunoregulatory effects during fungal infection in a manner independent of their role in PCD responses, but chiefly by regulating cytokine responses." (PMID 28919893, 2017).
glaucoma (1 paper, 2014). Increased pressure in the eyeball due to obstruction of the outflow of aqueous humor. "Furthermore, FADD is upregulated in RGCs subjected to ocular hypertension, and FasL-expressing microglia can induce apoptotic RGC death in a spontaneous mouse glaucoma model." (PMID 24714389, 2014).
Glucose intolerance (1 paper, 2016). Glucose intolerance (GI) can be defined as dysglycemia that comprises both prediabetes and diabetes. "Adipocyte‐specific FADD deletion activated insulin signaling pathways in skeletal muscle, liver, and WAT, thereby contributing to the improvement of HFD‐induced whole‐body glucose intolerance." (PMID 27357657, 2016).
gout (1 paper, 2019). A condition characterized by painful swelling of the joints, which is caused by deposition of urate crystals. "In conclusion, our results advance our understanding of the mechanisms contributing to FADD protein regulation in human monocytes/macrophages and provide some important clues on its potential clinical relevance in chronic rheumatic diseases such as gout or RA." (PMID 30804327, 2019). "Altogether, these data suggest that FADD secretion in the synovial fluid from gout patients might result from NLRP3 inflammasome activation by MSU crystals." (PMID 30804327, 2019).
HIV-1 infection (1 paper, 2025). The type species of lentivirus and the etiologic agent of acquired immunodeficiency syndrome (AIDS). "In Jurkat cells lacking Fas-associated protein with death domain [FADD], a key adaptor in apoptotic signaling, there was a significant increase in necroptosis upon HIV-1 infection." (PMID 40072080, 2025).
hypopharyngeal cancer (1 paper, 2021). Carcinoma, predominantly squamous cell, arising from the epithelial cells of the hypopharynx. "Therefore, it can be seen that FADD is most likely to play a role in the chemotherapy resistance of hypopharyngeal cancer, which is quite consistent with the conclusion drawn by our proteomics, which also fully arouses our interest in FADD." (PMID 34262870, 2021).
inflammatory bowel disease (1 paper, 2020). A spectrum of small and large bowel inflammatory diseases of unknown etiology. "Indeed, loss of Caspase‐8 or FADD induces TNF‐mediated necroptosis and inflammatory lesions in murine intestinal epithelium, resembling the pathology of inflammatory bowel disease." (PMID 33314666, 2020).
inflammatory skin disease (1 paper, 2020). Inflammatory skin disorders covers a broad category that includes many conditions ranging in severity, from mild itching to grave medical health complications These disorders are common in people of all ages and races. "The key molecules in cell death signaling, caspase-8, FADD, and cFLIP, were shown to be essential for the maintenance of skin homeostasis, since loss of any of these molecules resulted in severe inflammatory skin disease." (PMID 33238518, 2020). "FADD or caspase-8 deficiency in skin results in spontaneous necrosis of keratinocytes in vivo, causing an inflammatory skin disease." (PMID 33238518, 2020).
influenza (1 paper, 2021). An acute viral infection of the respiratory tract, occurring in isolated cases, in epidemics, or in pandemics; it is caused by serologically different strains of viruses (influenzaviruses) designated A, B, and C, has a 3-day incubation period, and usually lasts for 3 to 10 days. "Caspases CASP3, CASP8, CASP10, and FAS associated death domain (FADD) are important for apoptosis which is a pathway downregulated upon influenza vaccination." (PMID 34695164, 2021).
insulinoma (1 paper, 2025). "Isolated mouse islets and insulinoma cell lines were analyzed to assess the expression of Fas, Fas ligand, and Fas-associated death domain (FADD) using techniques such as reverse transcription-polymerase chain reaction (RT-PCR), WB, and immunofluorescence." (PMID 39859479, 2025).
intervertebral disc degeneration (1 paper, 2023). "Wang HQ published the article entitled “Deregulated miR-155 promotes Fas-mediated apoptosis in human intervertebral disc degeneration by targeting FADD and caspase-3” in The Journal of Pathology in 2011, which was cited 163 times and ranked second in terms of citations." (PMID 37061725, 2023).
invasive ductal carcinoma (1 paper, 2014). "As a result, we found that FADD expression was associated with T stage, showed a combined score of TMEM16A, FADD, and PPFIA1 expressions and was associated with perineural invasion and disease-free survival in the invasive ductal carcinoma cases." (PMID 24886289, 2014). "In the current study, we screened the expressions of TMEM16A, FADD, and PPFIA1 in invasive ductal carcinoma of the breast." (PMID 24886289, 2014). "Therefore, we screened expressions of FADD and closely located genes (PPFIA1 and TMEM16A) and evaluated the expressions to find clinical significance in invasive ductal carcinoma of the breast." (PMID 24886289, 2014).
Lewis lung carcinoma (1 paper, 2017). "FADD deficiency did not sensitize these cells to necroptosis because neither A549 nor murine Lewis lung carcinoma (3LL) cells express detectable levels of RIPK3." (PMID 28212753, 2017).
lupus (1 paper, 2015). "As presented in this work, GM extract attenuates lupus-associated cardiac apoptosis in lupus-prone mice by down-regulating TNF-α/TNF-α receptors and Fas/FADD and reducing amounts of activated caspase-9, Bax, activated caspase-8 and activated caspase-3." (PMID 25985203, 2015).
Lymphadenopathy (1 paper, 2019). Enlargement (swelling) of a lymph node. "We found that the lpr phenotype, characterized as lymphadenopathy and splenomegaly, became apparent in FADD−/− RIPK3−/− double knockout (DKO) mice past 3 months of age (middle)." (PMID 30867408, 2019).
lymphopenia (1 paper, 2019). Reduction in the number of lymphocytes. "Furthermore, Tradd−/− mice contain a normal lymphoid compartment, while conditional deletion of RIPK1 or FADD results in T lymphopenia in the periphery." (PMID 30741936, 2019).
mesothelioma (1 paper, 2022). A usually malignant and aggressive neoplasm of the mesothelium which is often associated with exposure to asbestos. "The same effects on MEDI3039 sensitivity were detected in analogous TNFRSF10B, FADD, CASP8, and BID cRNA KO models derived from two additional rTRAlL-sensitive mesothelioma cell lines H2804 and NCI-H28." (PMID 35086954, 2022). "To validate the most significant genes identified across both models as conferring resistance to rTRAIL, we used synthetic crRNA to knock out expression of FADD, BID, CASP8, and TNFRSF10B (TRAIL-R2) in the rTRAIL-sensitive MSTO-211H mesothelioma cell line stably expressing Cas9." (PMID 35086954, 2022).
Myocardial fibrosis (1 paper, 2023). "Studies have shown that GRb1 improves structural and metabolic disturbances in HF rats, inhibits myocardial fibrosis, and enhances cardiac energy metabolism by suppressing the abnormal upregulation of FADD and increasing ATP generation." (PMID 38138606, 2023).
ocular coloboma (1 paper, 2019). "LOH affecting FADD was reported in ocular coloboma; since PAX2 mutations have been identified as one of the most common causes of coloboma, it could be speculated that reduced FADD expression—either due to LOH or to mutations in PAX2 causing regulation of transcription—would play a role in coloboma." (PMID 31569512, 2019). "Hemizygosity affecting FADD has also been reported in ocular coloboma, a manifestation of otodental syndrome or, as more recently re-named, the chromosome 11q13 deletion syndrome." (PMID 31569512, 2019).
oropharyngeal cancers (1 paper, 2019). Carcinoma, predominantly squamous cell, arising from the epithelial cells of the oropharynx. "A similar differential analysis in the HPV- cohort indicated a panel completely distinct from the HPV+ oropharyngeal cancers; FADD (Fas Associated via Death Domain, 41%), FKBP9 (FKBP Prolyl Isomerase 9, 24%), FLNA (Filamin A, 24%) and DNMT3B (DNA Methyl transferase 3 Beta, 18%) with high prevalence." (PMID 31310629, 2019).
osteoarthritis (1 paper, 2019). A noninflammatory degenerative joint disease occurring chiefly in older persons, characterized by degeneration of the articular cartilage, hypertrophy of bone at the margins and changes in the synovial membrane. "However, we detected high concentrations of both FADD and IL-1β in the knee synovial fluid from patients with gout attack, as compared to patients with osteoarthritis (OA), considered as a non-inflammatory rheumatic disease." (PMID 30804327, 2019).
osteogenesis imperfecta (1 paper, 2025). Osteogenesis imperfecta (OI) comprises a heterogeneous group of genetic disorders characterized by increased bone fragility, low bone mass, and susceptibility to bone fractures with variable severity. "Five RGDs were specific to Sheikh caste, including cerebral dysgenesis neuropathy, FADD gene defect, osteogenesis imperfecta, spinal muscular atrophy, and tyrosinemia." (PMID 41516090, 2025).
Parkinson's (1 paper, 2025). "Our findings indicate that miR-361-5p regulates the expression of HMOX1 and FADD, suggesting that miR-361-5p may represent a potential therapeutic target in Parkinson's disease." (PMID 41203125, 2025).
periodontal disease (1 paper, 2021). "Among common oral inflammatory conditions, the presence of epigenetic modifications in proinflammatory cytokines such as Fas-associated death domain protein (FADD), interleukin-12 subunit beta (IL-12B), and interleukin-4 receptor (IL-4R) has been associated with periodontal disease." (PMID 34370052, 2021).
prion disease (1 paper, 2024). A transmissible disease that is caused by a protein that is able to induce abnormal folding of normal cellular proteins, leading to characteristic spongiform brain changes, which are associated with neuronal loss without an inflammatory response. "Collectively, the result suggests the expression of FADD is static in mouse prion disease." (PMID 38802941, 2024). "Therefore, the study of FADD became warranted in this mouse prion disease." (PMID 38802941, 2024). "Interestingly, not a single study so far has focused into the crucial role of TRADD, TRAF2, FADD, and RIPK1 in prion diseases." (PMID 38802941, 2024).
psoriasis (1 paper, 2023). An autoimmune condition characterized by red, well-delineated plaques with silvery scales that are usually on the extensor surfaces and scalp. "Several atypical NF-kB pathways were enriched and activated in psoriasis, such as NF-kB activation through FADD RIP-1 Pathway mediated by caspase 8 and10, TNFR2 and Dectin1 mediated noncanonical NF-kB pathway." (PMID 37861483, 2023).
pulmonary TB (1 paper, 2020). "In conclusion, M. tuberculosis Beijing strain was associated with severe pulmonary damage, inhibited FADD expression and reduced apoptosis level of macrophages derived from pulmonary TB patients." (PMID 32887662, 2020).
renal fibrosis (1 paper, 2023). A final common manifestation of a wide variety of chronic kidney diseases characterized by glomerulosclerosis and tubulointerstitial fibrosis. "This evidence led us to understand that phosphorylation of FADD may lead to IgA nephritis and, ultimately, renal fibrosis." (PMID 38074159, 2023).
reovirus infection (1 paper, 2010). "The adaptor molecule FADD is required for cleavage of Bid following reovirus infection of HEK293 cells." (PMID 20617182, 2010).
Salmonella Infections (1 paper, 2020). Infections with bacteria of the genus SALMONELLA. "In this study, we show that TRADD, FADD, and RIPK1 are GlcNAcylated by NleB, TRADD is GlcNAcylated by SseK1, and TNFR1 is GlcNAcylated by SseK3 during EPEC or Salmonella infection, which are consistent with previous studies." (PMID 32432056, 2020).
schizophrenia (1 paper, 2025). A major psychotic disorder characterized by abnormalities in the perception or expression of reality. "In an animal model of schizophrenia, there was no change in levels of Fas receptor and the adaptor protein FADD in cortical area." (PMID 41010622, 2025). "The levels of the adaptor protein FADD and FADD mRNA were not altered in the brains of patients with schizophrenia." (PMID 41010622, 2025).